USP22 (ubiquitin specific peptidase 22)
Diseases named in the same sentence as USP22 in open-access papers (continued):
Sharing a sentence is not in itself a finding about the gene and the disease.
tumor (continued). "The expression of Ubiquitin-specific protease 22 (USP22) in salivary ACC (SACC) was higher in the tumor group than in the adjacent normal group, which was associated with a poor prognosis." (PMID 34350460, 2021). "We extended that further by showing that USP22 deubiquitination was associated with SIRT1 stabilisation, subsequently transducing Akt and ERK tumour survival signal." (PMID 34226501, 2021). "Studies have shown that overexpression of USP22 can enhance the inhibitory effect of cell cycle inhibitors such as p21 and enhance the proliferation of tumor cells, thus promoting the occurrence and development of tumors." (PMID 33884267, 2021). "We recently identified an unexpected tumor-suppressive function of USP22 in CRC and detected intestinal inflammation after Usp22 deletion in mice." (PMID 33920268, 2021). "Conditional deletion of Usp22 in a mutant APC (APC1638N) mouse model resulted in induced aggressive tumor growth with increased proliferation and angiogenesis." (PMID 34503086, 2021). "The induction by USP22 promotes tumour invasion and epithelial-to-mesenchymal transition (EMT), leading to downregulation of E-cadherin and upregulation of N-cadherin, vimentin and matrix metalloproteinases (MMP)." (PMID 34226501, 2021). "Conversely, the knockdown by USP22 shRNA attenuated the tumour growth and invasiveness in vitro and in vivo." (PMID 34226501, 2021). "Subsequent monitoring of tumor occurrence revealed a strong increase of disease-free survival in animals with tissue-specific Usp22 knockout (median survival: 335 days) compared to Usp22wt/wt animals (median survival: 166 days)." (PMID 34007022, 2021). "In implantation xenografts, USP22 overexpression stimulated tumour growth and metastasis to the lungs of mice." (PMID 34226501, 2021). "The results showed that the group that overexpressed miR-30a-5p and suppressed USP22 showed a decrease in tumor size and weight (p < 0.05)." (PMID 34350172, 2021). "Loss of USP22 expression delays prototypical TBZ‐induced necroptosis in several human tumor cell lines, and necroptosis resistance positively correlates with USP22 expression levels, relying on the catalytic USP22 DUB activity." (PMID 33369872, 2021). "SIRT1 knockdown inhibited USP22-induced HCCC tumour growth, and the sizes and weights of these tumours were almost half of the HCCC-USP22 (p < 0.05)." (PMID 34226501, 2021). "We collected 57 paired iCCA and adjacent normal tissues and analysed their USP22 mRNA expression by qPCR, and showed that USP22 was elevated across all tumour tissues, particularly those with invasive lesions (p < 0.05)." (PMID 34226501, 2021). "USP22 has been reported to promote tumor progression by participating in the mediation of DNA repair processes." (PMID 34545063, 2021). "A huge impact arose on the STAT1 signaling pathway in knockdown of USP22, which will change the developmental process of tumor cells." (PMID 32294625, 2020). "More recent studies have shown that USP22 is not only a marker of aggressive tumors but also a tumor inducing factor." (PMID 32616828, 2020). "A study discovered that miR-30b-5p is a tumor suppressor in CRC through the USP22/Wnt/β-catenin signaling axis." (PMID 32280704, 2020). "Some results show that USP22 is overexpressed in many tumor types and affects tumorigenesis and development by affecting cell cycle." (PMID 32850399, 2020). "In hepatocellular carcinoma, the enhanced expression of USP22 was shown to be an independent factor for a poor prognosis with tumor progression." (PMID 34660907, 2020). "The mice inoculated with USP22-overexpressing SGC7901 cells had significantly greater tumor mass than those in the control group." (PMID 32063746, 2020).
tumor (continued). "USP22 was identified to highly express in LUAD through immunohistochemical experiment of the tumor tissues." (PMID 32294625, 2020). "USP22 reduction at its mRNA and protein levels was observed in the tumor tissues from the mice with USP22-silenced BGC-823-luc cells." (PMID 31689236, 2019). "The degree of tumor differentiation negatively correlated with the level of USP22 protein expression in the GC tissue samples." (PMID 31689236, 2019). "TUNEL assay analysis of xenograft tumor sections showed significantly higher number of apoptotic cells in the USP22 knockdown group compared with the control group." (PMID 31689236, 2019). "Intriguingly, in a USP22-deficient context, the further inhibition of HSP90 activity using Ganetespib effectively reduced tumor growth in vitro and in vivo." (PMID 31801945, 2019). "High USP22 expression correlated with large tumor size, tumor differentiation, tumor infiltration, local lymph node metastasis, distant metastasis, and TNM stage." (PMID 31689236, 2019). "We established tumor xenografts by subcutaneously injecting USP22 knockdown or control BGC-823-luc cells into 6-week-old male SCID mice (n = 5 each)." (PMID 31689236, 2019). "Our study also shows that USP22 silencing in GC cells decreases cell proliferation and induces cell cycle arrest and apoptosis in vitro, and suppresses tumor growth and metastasis in vivo." (PMID 31689236, 2019). "In vivo experiments reveal that USP22 knockdown in GC cells significantly reduces xenograft tumor growth and lung metastasis in SCID mice." (PMID 31689236, 2019). "We then investigated the in vivo role of USP22 in tumor growth and metastasis by establishing tumor xenograft and metastasis models in SCID mice." (PMID 31689236, 2019). "Remarkably, silencing USP22 reduced the tumor volume of BEL/FU cells treated with 5‐FU (BEL/FU control shRNA cells treated with 5‐FU vs BEL/FU USP22 shRNA treated with 5‐FU, 945 ± 545 mm3 vs 372 ± 228 mm3, P < 0.05)." (PMID 28417539, 2017). "Consistent with the in vitro observations, silencing USP22 led to a dramatic decrease in tumor volume and weight compared with the control cells, and also enhanced chemosensitivity to 5-Fu in vivo." (PMID 28445968, 2017). "Significant correlations were found between USP22 expression and the tumor size, tumor differentiation and TNM stage." (PMID 28445968, 2017). "Primary tumor sections from 123 CRC patients were analyzed by IHC to assess the correlations between USP22 and AP4 expression and clinical characteristics." (PMID 28427243, 2017). "Down-regulated USP22 was observed in tumor tissues derived from USP22-depleted cells, with lower mRNA expression of CD133 and OCT4 compared to that of the tumor tissue from control cells." (PMID 28415621, 2017). "The frequency of KI67-positive nuclear staining was substantially decreased in tumor tissues from USP22-silenced cells compared to those of the controls (30% versus 100%, respectively)." (PMID 28415621, 2017). "The tumor-bearing mice were sacrificed at 30 d, and the tumors formed from USP22-depleted cells weighed less than that of the controls." (PMID 28415621, 2017). "Consistent with in vitro findings, downregulation of USP22 in ATC cells impeded tumor growth and lung metastasis in vivo." (PMID 27145278, 2016). "It is clear that USP22 is involved in tumor progression because it is not only increased at the mRNA level but also at the protein level." (PMID 27057639, 2016). "Whereas palpable tumors formed one week after tumor cell implantation in both groups, the growth of tumors derived from USP22 knockdown 8505C-luc cells were compromised when compared with those from control 8505C-luc cells." (PMID 27145278, 2016). "USP22 downregulation was observed in the tumor tissues from the mice with USP22-silenced 8505C-luc cells." (PMID 27145278, 2016). "Collectively, these results suggested that USP22 depletion attenuates tumor growth and metastasis of ATC." (PMID 27145278, 2016).
tumor (continued). "A number of studies have suggested an important function for USP22 during tumorigenesis and/or tumor progression." (PMID 26431380, 2015). "High USP22 expression was mainly found in patients with more advanced tumor stages (50/74 in stages III+IV vs. 8/30 in stages I+II, p = 0.000) and high-grade tumors (23/24 in grades 3-4 vs. 35/80 in grades 1-2, p = 0.000)." (PMID 25909224, 2015). "Both the growth speed and average tumor size were dramatically reduced in mice that had been injected with USP22-knockdown HCT116 cells." (PMID 27030811, 2015). "In this study, we demonstrated that USP22 is overexpressed in human NSCLC tumor tissues and cell lines." (PMID 25547493, 2014). "To date, many studies demonstrate that USP22 represent a novel prognostic biomarker in tumor progression and oncogenesis." (PMID 24466336, 2014). "Recently, increasing evidence shows that Ubiquitin-specific protease 22 (USP22) have been recognized as a novel histone deubiquitinating enzyme, which is involved in tumor development and progression." (PMID 24466336, 2014). "Because the USP22 gene is abnormally activated in various human tumor cells, its promoter activity was investigated in both cultured HFL1 and HeLa cell lines." (PMID 23300749, 2012). "Promoter deletion analysis showed that the sequence between −210 and −7 contains the basal promoter for USP22 in human fibroblast and tumor cells." (PMID 23300749, 2012). "It has been documented that a key regulator of cell cycle, p21, is regulated by USP22, and depletion of USP22 results in a G1 phase cell-cycle arrest in human tumor cells." (PMID 23300749, 2012). "Ubiquitin-specific processing enzyme 22 (USP22) plays a direct role in regulating cell cycle, and its overexpression has been reported to be involved in tumor progression." (PMID 23300749, 2012). "These constructs were transfected into human lung fibroblast (HFL1) or human tumor cells (HeLa) to determine the sequence elements required for USP22 promoter activity." (PMID 23300749, 2012). "Moreover, considering the importance of USP22 in immune regulation and clinical treatment, targeting USP22 to prevent tumour biological processes and improve immunotherapy is worthy of attention." (PMID 41909123, 2026). "Indeed, both the recruitment of EZH2 to the promoter regions of B2m and H2Kb and their H3K27me3 modification levels, was decreased in USP22-null tumor cells." (PMID 41252204, 2025). "Integrated analysis of 57 paired iCCA tissues via qPCR, IHC, and TCGA data revealed significant USP22 overexpression in tumors, which independently correlated with tumor size > 5 cm, microvascular invasion, lymph node metastasis, and poor prognosis, suggesting its value as a prognostic biomarker." (PMID 41301681, 2025). "To further delineate underlying molecular mechanisms by which USP22 specifically controls EZH2 protein expression in tumor cells, we first determined whether USP22 interacts with EZH2." (PMID 41252204, 2025). "Given its role in tumor biology, USP22 is being explored as a potential therapeutic target, aiming to develop novel inhibitors that could enhance the effectiveness of existing treatments and improve outcomes for NSCLC patients." (PMID 40075700, 2025). "Additionally, the tumor suppressive efficacy of Usp22 inhibition was modest when MC38 tumor cells were implanted into RAG1-KO mice." (PMID 41252204, 2025). "USP22 is a negative regulator of MHC-I–mediated neoantigen presentation in tumor cells." (PMID 41252204, 2025). "Importantly, substantially lower β2M expression levels along with a markedly reduced intratumoral CD8+ T cell infiltration were detected in USP22 high compared with low tumor groups." (PMID 41252204, 2025). "Elevated levels of USP22 in NSCLC have been associated with poor prognosis, as they may facilitate tumor cell survival and resistance to apoptosis." (PMID 40075700, 2025).
tumor (continued). "Moreover, ELISA analysis detected a substantial increase in both IFN-γ and TNF-α secretion in the supernatant when CD8+ OT-I T cells were cocultured with Usp22 KO or pharmacological inhibition tumor cells." (PMID 41252204, 2025). "Indeed, reconstitution of Ezh2, but not its inactive methyltransferase mutant either by F667I mutation, or by deletion of the catalytic SET domain, fully reversed MHC-I expression levels in Usp22-null tumor cells." (PMID 41252204, 2025). "USP22 also regulates normal cell-cycle progression; hence, nanocarrier- or tumor-targeted delivery systems are required to improve the therapeutic index and guard against resistance driven by compensatory activation of other deubiquitinases or epigenetic regulators." (PMID 41301681, 2025). "The increase in MHC-I expression following USP22 inhibition may potentially reduce NK cell–mediated tumor killing." (PMID 41252204, 2025). "We focused on revealing the impact of USP22‐mediated EV secretion on tumor progression." (PMID 39101247, 2024). "Additionally, protein blotting showed that USP22 expression was significantly upregulated in matching tumour tissues than in neighbouring tissues." (PMID 39661501, 2024). "In addition, pharmacological inhibition of USP22 using the USP22i-S02 compound effectively abrogated the growth capacity, clonogenic potential, tumor sphere formation capacity and migratory behavior of TNBC cell lines." (PMID 38347585, 2024). "However, deletion of Usp22 significantly decreased tumor burden and increased survival of MMTV-NIC mice." (PMID 38236941, 2024). "USP22 plays a complex role in carcinogenesis, immune escape, and tumor resistance to drugs." (PMID 39143031, 2024). "Notably, although knocking down USP22 only mildly reduced tumor growth, it significantly increased the sensitivity of tumors to Taz." (PMID 38520088, 2024). "Stable RALY promotes tumor growth by regulating the ALYREF-dependent nuclear export of USP22 mRNA." (PMID 38993567, 2024). "This lack of effect could indicate a different mode of action for USP22 in tumor formation or progression, or it may reflect the already very high activity and expression of the rat NEU oncogene in these mice." (PMID 38236941, 2024). "However, complete deletion of Usp22 significantly delayed tumor formation (T50 214 days) with some mice remaining tumor free for almost 300 days." (PMID 38236941, 2024). "Low expression of USP22 in tumor cells affects the anti-tumor capability of immune cells." (PMID 39223632, 2024). "Similarly, USP22 significantly impacts cell proliferation and tumor growth by regulating the oncogene c‐Myc." (PMID 39678489, 2024). "USP22‐mediated EV secretion contributes to invadopodia formation, which are specific and critical docking and secretion sites for MVBs, thus forming a positive feedback loop to promote tumor metastasis." (PMID 39101247, 2024). "Since USP22 acts in highly context- and tumor-specific manners, our findings might open novel therapeutic opportunities to re-sensitize ATRA-resistant, relapsed APL patients to ATRA treatment by simultaneous inhibition of USP22." (PMID 38467608, 2024). "Similarly, ubiquitin-specific peptidase 22 (Usp22) has been shown to regulate Foxp3 expression at the transcriptional level, with Usp22 knockout demonstrating beneficial outcomes in several mouse tumor models." (PMID 39538305, 2024). "Loss of one allele of Usp22 (Usp22FL/+) had no impact on the kinetics of tumor formation in MMTV-NIC mice." (PMID 38236941, 2024). "High levels of USP22 expression in HCC correlate with the expression of PPARγ, ATP‐citrate lyase (ACLY), and acetyl‐CoA carboxylase, and are associated with poor prognosis, underscoring its role in lipid metabolism and tumor progression." (PMID 39678489, 2024).
tumor (continued). "Based on the National Center for Biotechnology (NCBI) database, we queried genes related to the ECM, TME, and tumor metastasis and established co‐expression modules to identify the roles of USP22 in the ECM, TME, and tumor metastasis by weighted gene co‐expression network analysis (WGCNA)." (PMID 39101247, 2024). "Wild‐type MC38 or MC38 USP22‐knockdown subcutaneous tumor models were established in C57BL/6J mice." (PMID 38520088, 2024). "Mice that received injections of USP22‐deficient B16F10 cells exhibited a reduced metastatic burden, characterized by a lower number of lung micro‐metastases per lung section, as detected by hematoxylin–eosin (H&E) staining of tumor nodule specimens." (PMID 39135915, 2024). "Additionally, patient‐derived tumor xenograft (PDX) models with different expression levels of USP22 were used to evaluate the antitumor efficacy of rapamycin." (PMID 38045832, 2023). "Furthermore, we provided the evidence to show that knockdown of USP22 inhibited HCC growth in tumor-bearing nude mice." (PMID 36906615, 2023). "The results showed that, overexpression of USP22 significantly promoted the growth of HCC, and knockdown of ZEB1 inhibited the effect of USP22 on tumor growth, suggesting that ZEB1 was involved in the development of HCC, and the promotion of HCC growth by USP22 was partially related to ZEB1." (PMID 36906615, 2023). "Two xenograft mouse models were used to examine the role of USP22 in tumor growth in vivo." (PMID 38045832, 2023). "In addition, the expression of USP22 was also positively correlated with that of VEGFA in xenograft tumor." (PMID 36906615, 2023). "It has been reported that USP22 plays an important role in tumor drug resistance." (PMID 36906615, 2023). "Injection of VEGFA-165 partially restored the tumor growth inhibition induced by USP22 knockdown." (PMID 36906615, 2023). "The inhibition of USP22 enhances the cytotoxicity of T cells and reduces tumor growth." (PMID 37415977, 2023). "USP22 in PC cells interacts with SAGA/STAGA to affect the immune microenvironment, and USP22 deficiency promotes T-cell and NK cell infiltration and inhibits tumor metastasis." (PMID 37529035, 2023). "Therefore, further studies should be performed to detect the signal transduction pathway and the corresponding regulation mechanism of USP22 in GC cells and to further understand the role of USP22 in tumor genesis and the development of GC." (PMID 35784926, 2022). "In addition, the role of USP22 in the anti-tumor immunity of NSCLC has attracted more and more attention." (PMID 35935969, 2022). "Given the important role of USP22 in tumor progression, USP22 may become a new potential target for tumor therapy." (PMID 35935969, 2022). "Collectively, this evidence suggests that altered expression of Usp22 might provide a way for tumor cells to survive in hypoxic conditions, allowing the escape of cells from the necrotic area toward vascularized tissues." (PMID 35626719, 2022). "Interestingly, in 19 of 30 cases all the palisade areas present in the sections showed a significant increase in Usp22 expression when compared with the oxygenated areas of the same tumor." (PMID 35626719, 2022). "USP22 is a deubiquitinating enzyme that can affect tumor malignancy, metastasis, and prognosis." (PMID 35965557, 2022). "In order to understand if Usp22 similarly to Ubp8, might have links with mitochondria, we then immunostained tumor specimens with anti-Parkin." (PMID 35626719, 2022). "Treg-specific ablation of USP22 leads to reduced tumor volume in multiple cancer models." (PMID 35935969, 2022). "How USP22 senses tumor microenvironment signals to regulate PD-L1, and whether other deubiquitinating enzymes are able to sense these signals, remains unknown." (PMID 35884430, 2022). "Additionally, the downregulation of USP22 results in tumor cells remaining arrested at the G1 phase via p21 stabilization." (PMID 36613989, 2022).